IGLV2-11 (immunoglobulin lambda variable 2-11)
Description:
V region of the variable domain of immunoglobulin light chains that participates in the antigen recognition. Immunoglobulins, also known as antibodies, are membrane-bound or secreted glycoproteins produced by B lymphocytes. In the recognition phase of humoral immunity, the membrane-bound immunoglobulins serve as receptors which, upon binding of a specific antigen, trigger the clonal expansion and differentiation of B lymphocytes into immunoglobulins-secreting plasma cells. Secreted immunoglobulins mediate the effector phase of humoral immunity, which results in the elimination of bound antigens. The antigen binding site is formed by the variable domain of one heavy chain, together with that of its associated light chain. Thus, each immunoglobulin has two antigen binding sites with remarkable affinity for a particular antigen. The variable domains are assembled by a process called V-(D)-J rearrangement and can then be subjected to somatic hypermutations which, after exposure to antigen and selection, allow affinity maturation for a particular antigen.
Synonyms: IGLV211; V1-3
Tractability: Antibody: its Gene Ontology location is reachable by antibodies, with high confidence; UniProt places it where antibodies can reach, with medium confidence; UniProt predicts a signal peptide or a membrane-spanning region.
Gene: Immunoglobulin variable (V) gene on chromosome 22 (22,792,491 to 22,793,007, forward strand). Ensembl gene ENSG00000211668.
Subcellular location: Secreted; Cell membrane
Pathways (Reactome):
Immune System: Antigen activates B Cell Receptor (BCR) leading to generation of second messengers; CD22 mediated BCR regulation; Classical antibody-mediated complement activation; FCERI mediated Ca+2 mobilization; FCERI mediated MAPK activation; FCERI mediated NF-kB activation; FCGR activation; Fc epsilon receptor (FCERI) signaling; Immunoregulatory interactions between a Lymphoid and a non-Lymphoid cell; Initial triggering of complement; Regulation of Complement cascade; Regulation of actin dynamics for phagocytic cup formation; Role of LAT2/NTAL/LAB on calcium mobilization; Role of phospholipids in phagocytosis
Disease: FCGR3A-mediated IL10 synthesis; FCGR3A-mediated phagocytosis; Potential therapeutics for SARS
Hemostasis: Cell surface interactions at the vascular wall
Vesicle-mediated transport: Scavenging of heme from plasma
Gene Ontology:
Molecular function: antigen binding
Biological process: immune response
Cellular component: extracellular region; immunoglobulin complex; plasma membrane
Homologues: Paralogues in human: IGLV2-8 (92% identical), IGLV2-14 (90% identical), IGLV2-18 (88% identical), IGLV2-23 (87% identical), IGLV1-40 (72% identical), IGLV2-33 (71% identical), IGLV1-50 (68% identical), IGLV1-44 (65% identical), IGLV1-47 (64% identical), IGLV1-51 (64% identical), IGLV6-57 (63% identical), IGLV1-36 (62% identical), and 81 more.
Diseases named in the same sentence as IGLV2-11 in open-access papers:
IGLV2-11 is named in the same sentence as 4 diseases in open-access papers, as found by Europe PMC text mining. Sharing a sentence is not in itself a finding about the gene and the disease. The quoted sentences say what the papers report.
open-angle glaucoma (1 paper, 2023). Chronic outflow obstruction of the eye's drainage canals that can lead to increased internal eye pressure and optic nerve damage. "The CDR1 peptide SCTGTSSDVGGYNYVSWYQ (homologous to IGLV2-11*03) was identified first as a potential biomarker candidate in primary open-angle glaucoma (POAG) patients and offers promising properties as a therapeutic agent." (PMID 37509196, 2023).
IGLV2-11 also shares sentences with these, for which no sentence is quoted: COVID-19 (1 paper); inflammation (1); viral infection (1).